ATP2A1 (ATPase sarcoplasmic/endoplasmic reticulum Ca2+ transporting 1)
Diseases named in the same sentence as ATP2A1 in open-access papers (continued):
Sharing a sentence is not in itself a finding about the gene and the disease.
colorectal cancer (3 papers, 2022 to 2025). A primary or metastatic malignant neoplasm that affects the colon or rectum. "For the first time, we used sufficient evidence to show that ATP2A1 was a risk factor for colorectal cancer, and the high expression of ATP2A1 was associated with the poor prognosis of colorectal cancer patients." (PMID 35783262, 2022). "In colorectal cancer, ATP2A1 expression was markedly and negatively linked with the infiltration abundance of CD8 + T cells, suggesting that ATP2A1-promoted tumor growth may be relevant to the immune." (PMID 41246353, 2025). "This study demonstrates for the first time that ATP2A1 is a potential pathogenic factor, which may play a significant role in colorectal cancer." (PMID 35783262, 2022). "Additionally, we analyzed the relationship between immune infiltration and ATP2A1 expression in colorectal cancer patients and found some immune cell populations associated with ATP2A1 expression." (PMID 35783262, 2022). "Thus, the risk of poor prognosis of patients with colorectal cancer with ATP2A1 was determined." (PMID 35783262, 2022). "Furthermore, we revealed that ATP2A1 could significantly inhibit the proliferation of colorectal cancer cells by inhibiting the autophagy process and was associated with several immune cells, especially CD8 + T cells." (PMID 35783262, 2022). "In this study, we attempted to reveal the relationship between ATP2A1 expression and prognosis in colorectal cancer patients by bioinformatics analysis." (PMID 35783262, 2022). "In this study, we analyzed the relationship between ATP2A1 gene expression and the prognosis of colorectal cancer patients using the TCGA database." (PMID 35783262, 2022). "We used the TCGA database to reveal the relationship between ATP2A1 mRNA level and prognosis, methylation, and immune invasion in colorectal cancer." (PMID 35783262, 2022). "In order to explore whether the clinical characteristics of patients interfere with the impact of ATP2A1 on the prognosis of patients, the Cox model was used to comprehensively consider if ATP2A1 could be used as an independent risk factor for patients with colorectal cancer." (PMID 35783262, 2022). "Lastly, we further explored the mechanism of ATP2A1 function in colorectal cancer and verified the autophagy pathway by referring to the results of the KEGG analysis." (PMID 35783262, 2022). "In our study, we investigated the methylation levels of six methylation sites of ATP2A1 in colorectal cancer." (PMID 35783262, 2022). "The innovation of this study is to reveal for the first time that the high expression of ATP2A1 in colorectal cancer can significantly reduce the overall survival time of patients and expand its functional regulation mechanism as a pathogenic molecule." (PMID 35783262, 2022). "In this study, we explored the value of ATP2A1 as a biomarker in predicting the prognosis of colorectal cancer patients." (PMID 35783262, 2022). "First, we used RT-qPCR in two colorectal cancer cells (HCT116, SW480) and colorectal normal mucosal cells (FHC) and found that the expression level of ATP2A1 was also significantly increased in two colorectal cancer cells, especially in SW480 cells." (PMID 35783262, 2022). "We found that the hypermethylation of ATP2A1 was negatively correlated with tumor progression, which suggested that ATP2A1 might be an oncogene and plays a role in promoting the progression of colorectal cancer." (PMID 35783262, 2022). "However, this is also the innovation of this study, which broadens the molecular mechanisms of the cognitive function of ATP2A1 in colorectal cancer." (PMID 35783262, 2022). "Collectively, our results show that ATP2A1 may promote colorectal cancer cell proliferation through autophagy." (PMID 35783262, 2022). "Therefore, we applied the GO and KEGG analysis to explore the potential function of ATP2A1 in colorectal cancer." (PMID 35783262, 2022).
colorectal cancer (continued). "Univariate analysis showed that high expression of ATP2A1 resulted in poor prognosis in patients with colorectal cancer [p < 0.01, hazard ratio (HR) = 2.032 (95%CI (1.251–3.302))] and TNM stage, lymphatic invasion, and tumor stage are also independent risk factors [p < 0.01, hazard ratio (HR > 1)]." (PMID 35783262, 2022). "Collectively, our analysis revealed the prognostic value of ATP2A1 in colorectal cancer, determined the relationship between ATP2A1 epigenetic expression and clinical features, and enriched its potential role in tumor immunity of colorectal cancer." (PMID 35783262, 2022). "However, to avoid the deviation caused by the single data analysis results, we combined the three databases to complete a meta-analysis verifying the impact of ATP2A1 on the prognosis of patients with colorectal cancer." (PMID 35783262, 2022). "Therefore, this study uses adequate evidence to demonstrate the value of ATP2A1 in the prognosis of colorectal cancer and provides a new perspective for the pathogenesis and drug treatment of colorectal cancer." (PMID 35783262, 2022). "The results showed that the expression of ATP2A1 was increased in colorectal cancer." (PMID 35783262, 2022). "Subsequently, several small molecule drugs that can inhibit the expression of ATP2A1 were found in the CMap database, which may become a potential drug for the treatment of colorectal cancer." (PMID 35783262, 2022). "The KEGG analysis was used to study the possible signaling pathway of ATP2A1 in colorectal cancer." (PMID 35783262, 2022). "Our study revealed that ATP2A1 might be a key pathological factor of colorectal cancer and its potential mechanism of action." (PMID 35783262, 2022). "However, more physiological and pathological functions of ATP2A1 are unknown, especially in colorectal cancer." (PMID 35783262, 2022). "Finally, knockdown of ATP2A1 in vitro could significantly reduce the proliferation of colorectal cancer cells." (PMID 35783262, 2022). "Therefore, this study attempts to demonstrate whether the high expression of ATP2A1 in patients with colorectal cancer is regulated by its methylation sites." (PMID 35783262, 2022). "Consequently, we speculated that ATP2A1 might be involved in the progression of colorectal cancer." (PMID 35783262, 2022). "Transcriptomic analysis via RNA sequencing revealed upregulation of genes implicated in colitis and colorectal cancer (CRC) progression, such as Anxa9, Atp2a1, and Hepacam2, in ERAP1+/− mice, regardless of sulfasalazine administration." (PMID 40977735, 2025).
dilated cardiomyopathy (3 papers, 2021 to 2025). Cardiomyopathy which is characterized by dilation and contractile dysfunction of the left and right ventricles. "Necroptosis, neutrophil extracellular trap formation, cardiac muscle contraction, and dilated cardiomyopathy, among others, are some pathways affected by downregulated proteins such as Pgam5, Slc25a4, and H2ax as well as Myl2, Myl3, Atp2a1, and Tpm2." (PMID 41011134, 2025). "In the cases of dilated cardiomyopathy, cardiac muscle contraction, and hypertrophic cardiomyopathy (B), seven downregulated proteins were enriched, including Myl2, Myl3, Myh7, Atp2a1, Tpm1, Tpm2, and Ttn." (PMID 39861068, 2024).
Duchenne muscular dystrophy (3 papers, 2013 to 2025). Duchenne muscular dystrophy (DMD) is a neuromuscular disease characterized by rapidly progressive muscle weakness and wasting due to degeneration of skeletal, smooth and cardiac muscle. "It has been shown before by qPCR that many “DM1-specific” splice events are shared between DM1 and Duchenne muscular dystrophy (DMD) including, among others, MBNL1, ATP2A1, TTN, TNNT2 and MEF2A/C." (PMID 40149583, 2025).
Cachexia (2 papers, 2024 to 2025). Severe weight loss, wasting of muscle, loss of appetite, and general debility related to a chronic disease. "These enzymes, along with thermogenic proteins (e.g., Ucp1, Sln, Ryr1 and Atp2A1) may be targetable to mitigate cachexia‐related fat loss." (PMID 40468964, 2025). "Based on these findings, we propose that ACT may exert its anti-cachexia effects through the regulation of inflammatory response and energy metabolism via multiple targets, including CYP3A4, CYP19A1, CYP2E1, TNF, BCL-2, RYR2, and ATP2A1." (PMID 39872045, 2024).
Darier disease (2 papers, 2017 to 2023). Darier disease (DD) is a keratinization disorder characterized by the development of keratotic papules in seborrheic areas and specific nail anomalies. "The genes disturbed by the CNVs mainly involve the SH2B1, TUFM, ATP2A1, and ATP2A2 genes, of which mutations of the single ATP2A2 gene in Darier disease have been found to be connected to the neuropsychiatric abnormalities frequently observed in Darier disease." (PMID 28680393, 2017).
hypertrophic cardiomyopathy (2 papers, 2024 to 2025). A condition in which the myocardium is hypertrophied without an obvious cause. "The hypertrophic cardiomyopathy pathway contains upregulated genes like sarcoplasmic/endoplasmic reticulum calcium ATPase 1 (ATP2 A1), myosin light chain 3 (MYL3) and troponin C, skeletal muscle (TNNC2)." (PMID 40708816, 2025).
Malignant hyperthermia (2 papers, 2014 to 2022). Malignant hyperthermia is characterized by a rapid increase in temperature to 39-42 degrees C. Malignant hyperthermia may occur in response to either inhalational anesthetics such as halothane, to muscle relaxants such as succinylcholine, or to exercise. "Malignant hyperthermia susceptibility was also significantly correlated with RYR1 mutations, so whether ATP2A1 is correlated with RYR1 is worth discussing." (PMID 35692882, 2022).
myotonic dystrophy type 1 (2 papers, 2020 to 2021). Steinert disease, also known as myotonic dystrophy type 1, is a muscle disease characterized by myotonia and by multiorgan damage that combines various degrees of muscle weakness, arrhythmia and/or cardiac conduction disorders, cataract, endocrine damage, sleep disorders and baldness. "In vertebrate systems, differential isoform regulation through development has long been appreciated, and in some disease states such as type 1 myotonic dystrophy, fetal or neonatal stage isoforms of Tnnt2, Atp2a1 (Serca1), and Ldb3 (Zasp) are inappropriately expressed." (PMID 34620214, 2021).
oropharyngeal cancer (2 papers, 2020 to 2021). Carcinoma, predominantly squamous cell, arising from the epithelial cells of the oropharynx. "A previous study also identified ATP2A1 as an important driver of human papillomavirus (HPV)-associated oropharyngeal cancer." (PMID 34831096, 2021).
ovarian carcinoma (2 papers, 2021 to 2022). A malignant neoplasm originating from the surface ovarian epithelium. "Furthermore, inhibition of ATP2A1 activity by curcumin disrupts the Ca2+ homeostasis and hence promotes apoptosis in ovarian cancer cells." (PMID 35509066, 2022).
prostate carcinoma (2 papers, 2015 to 2024). A carcinoma that arises from epithelial cells of the prostate gland. "Metformin upregulated p-eIF2α, CRT and CHOP, whereas miR-708-5p transfection increased the levels of GRP78, p-eIF2α, ATP2A1 and CHOP, indicating that both metformin and miR-708-5p can cause ER stress in prostate cancer cells." (PMID 26075749, 2015). "In prostate cancer from AA men, genes including known AR target genes TRIM63, ATP2A1, and ARHGAP28, showed a significant inverse correlation between gene expression and DNA methylation." (PMID 38566104, 2024).
Anxiety (1 paper, 2021). Intense feelings of nervousness, tension, or panic often arise in response to interpersonal stresses. "We identified two transcriptome-wide significant signals: TMEM106B for depression with anxiety (panel CMC DLPFC splicing, p = 1.23 × 10−6) and ATP2A1 for depression with weight gain (panel PsychENCODE, p = 1.34 × 10−6); no significant features were identified for TRD." (PMID 34158615, 2021).
Aortic Coarctation (1 paper, 2015). "None of these pathways were associated with Aortic Coarctation (MESH:D001017), but one DEG (ATP2A1) associated with Aortic Coarctation was located in the Hemostasis pathway." (PMID 26207811, 2015). "While no pathways identified by IPAD were associated with CoA, one individual DEG from the current investigation, ATP2A1, associated with Aortic Coarctation in IPAD was also located in the Hemostasis pathway." (PMID 26207811, 2015).
autism spectrum disorder (1 paper, 2022). A spectrum of developmental disorders that includes autism, and Asperger syndrome. "Similarly, microduplication of 16p11.2 comprising ATXN2L, TUFM, SH2B1, and ATP2A1 genes can lead to the onset of microcephaly and autism spectrum disorder." (PMID 35722491, 2022).
basal cell carcinoma (1 paper, 2022). A carcinoma involving the basal cells. "The expression of CACNA1S, ATP2A1, RYR1, and MYLK3 was upregulated in MAC compared with normal sweat glands and syringoma tumor cells and was generally negative in trichoepithelioma and infundibulocystic type basal cell carcinoma." (PMID 35509066, 2022). "We demonstrated that the CACNA1S, MYLK3, RYR1, and ATP2A1 proteins were more highly expressed in MAC tumor cells than in normal sweat glands and syringoma, while were generally negative in tumor cells of trichoepithelioma and basal cell carcinoma, infundibulocystic type." (PMID 35509066, 2022).
colitis (1 paper, 2025). Inflammation of the colon. "Atp2a1, a gene associated with increased risk of IBD, also showed a significant increase in expression in sulfasalazine-treated ERAP1+/− colitis mice compared to ERAP1+/− controls (p < 0.001)." (PMID 40977735, 2025). "Notably, mRNA expression levels of Anxa9 (p < 0.05), Atp2a1 (p < 0.001), and Hepacam2 (p < 0.01) were all significantly upregulated in ERAP1+/− colitis mice relative to WT colitis mice after sulfasalazine treatment, indicating its potential role in colitis pathogenesis and therapeutic response." (PMID 40977735, 2025).
congenital muscular dystrophy (1 paper, 2023). A muscular dystrophy that is characterized by diminished muscle tone (hypotonia), progressive muscle weakness and degeneration (atrophy), abnormally fixed joints, spinal rigidity, and delays in reaching motor milestones such as sitting or standing unassisted. "Finally, the variant in the ATP2A1 gene associated with congenital muscular dystrophy presented an LD of r2 = 0.88 with the lead SNP in both the ST GWAS for rump and the MT GWAS for muscular development traits." (PMID 38017417, 2023).
COVID-19 (1 paper, 2024). A disease caused by infection with severe acute respiratory syndrome coronavirus 2. "To date, variants in the ATP2A1 genes that are responsible for COVID-19 predisposition have not been reported." (PMID 38816514, 2024). "Furthermore, there were undetectable expression levels of ATP2A1, ATP2A3, ATP2B2, and ATP2B3 in the lungs of both COVID-19 patients and controls (Fig. EV1G)." (PMID 38816514, 2024).
depression (1 paper, 2021). "For both TMEM106B and ATP2A1, the colocalization analysis showed that the same causal SNP was likely affecting both the risk of anxious or weight gain depression and transcription." (PMID 34158615, 2021).
diabetic neuropathy (1 paper, 2022). A chronic, pathological complication associated with diabetes mellitus, where nerve damages are incurred due to diabetic microvascular injury involving small blood vessels that supply these nerves, resulting in peripheral and/or autonomic nerve dysfunction. "In line with our peak-CIPN dataset, mRNA of the actin-binding protein Actn3 and the ATPase Atp2a1 were increased 4 weeks after induction of diabetic neuropathy in rat DRG, while contrary to our findings, the expression of the myosins Mylpf and Mhy1 was decreased." (PMID 35250568, 2022).
keloid (1 paper, 2025). An irregularly shaped, elevated mark on the skin caused by deposits of excessive amounts of collagen during wound healing. "Additionally, 14 genes such as GRIN2D, HTR7, and CCKAR were found to be upregulated in the calcium signaling pathway, while 43 genes, including ATP2A1, ADCY8, and MCOLN3, were significantly downregulated, suggesting that calcium signaling plays a critical role in the pathology of keloids." (PMID 41562114, 2025).
Myalgia (1 paper, 2025). "Second, APC, ENO3, ACAD9, RNASEH1, FKTN, DYSF, and ATP2A1 are associated with Myalgia." (PMID 40831500, 2025).
myotonic dystrophy (1 paper, 2019). An inherited progressive disorder affecting the muscles. "Of note, ATP2A1 is one of the multiple RNA targets that are misspliced as a result of MBNL1 sequestration in myotonic dystrophy (DM) muscles." (PMID 30688039, 2019).
Obesity (1 paper, 2021). Accumulation of substantial excess body fat. "Other critical modulators of the obesity phenotype exist within the ATP2A1 locus, such as SH2B1, a gene involved in leptin and insulin signaling." (PMID 34489471, 2021).
steatosis (1 paper, 2026). Increased lipid within the cytoplasm of cells. "In our study, transcriptomic profiling further revealed that vitamin E restores the expression of genes encoding calcium-handling proteins, including atp2a1 (SERCA) and atp1b1b, which were downregulated with HCD-induced steatosis." (PMID 41596272, 2026).
ventilator-associated pneumonia (1 paper, 2025). Serious INFLAMMATION of the LUNG in patients who required the use of PULMONARY VENTILATOR. "In ventilator-associated pneumonia (VAP), distinct gene expression profiles have been identified, showing downregulation of genes like PIK3R3, ATP2A1, PI3, ADAM8, and HCN4." (PMID 39941194, 2025).
cancer (13 papers, 2014 to 2026). A tumor composed of atypical neoplastic, often pleomorphic cells that invade other tissues. "ATP2A1, a cancer-associated immunomarker, shows good affinity for HLC-018, a novel aniline-linked small molecule, indicating its potential as a drug target for the treatment of cancer." (PMID 37697373, 2023). "Several studies had shown that ATP2A1 was associated with apoptosis and immune responses in various cancers." (PMID 36120545, 2022). "The range of phenotypes with ATP2A1 mutations also includes malignant hyperthermia." (PMID 30688039, 2019). "ATP2A1, a crucial enzyme for the maintenance of intracellular calcium homeostasis, is also a cancer-related immune marker." (PMID 41246353, 2025). "Immunohistochemistry showed that ATP2A1 has higher expression in cancer than in adjacent normal tissue." (PMID 35754841, 2022). "First, we could not obtain more regulatory effects in the pathological process of tumors because there are few studies on ATP2A1 in malignant tumors." (PMID 35783262, 2022). "First, we analyzed the difference of the ATP2A1 mRNA expression in 42 paracancerous tissues and 488 cancer samples using TCGA data and prepared a K-M survival curve; univariate and multivariate analysis was used to evaluate the relationship between ATP2A1 expression and prognosis." (PMID 35783262, 2022). "qRT-PCR analysis showed that the mRNA expression levels of TIMP1, CDC25C, ATP2A1, and TIGD1 were upregulated in cancer cell lines compared to normal cell lines, whereas NRG1 and DMPK exhibited reduced expression in cancer cell lines." (PMID 41190067, 2025). "ATP2A1 expression negatively affected patient survival rates, especially in luminal, HER2-positive cancer and TNBC vs. normal controls, whereas ATP2A2 levels remained unaltered." (PMID 34684111, 2021). "In our eight signature genes (ARL6IP4, ATP2A1, CRYAB, ELFN2, MAP2, MAT1A, ORC1, and POU4F1), prior research has elucidated the expression and function of several genes involved in the initiation and progression of cancer." (PMID 41567198, 2025). "Immunohistochemical staining and WB showed that the expression of ATP2A1 in cancer tissues was significantly higher than that in normal tissues adjacent to the cancer." (PMID 35754841, 2022).